IL15 (interleukin 15)
Diseases named in the same sentence as IL15 in open-access papers (continued):
Sharing a sentence is not in itself a finding about the gene and the disease.
tumor (continued). "Additionally, BiKEs and TriKEs have been designed to further boost CAR-NK cell activity by simultaneously targeting tumor antigens and engaging CD16 on NK cells, with TriKEs additionally delivering IL-15 to support NK cell persistence and proliferation." (PMID 41511303, 2025). "Moreover, CAR-M would secrete IL-1, IL-2, and IL-15, which would upregulate CAR-NK cells and enhance their cytotoxicity against tumour cells." (PMID 40650066, 2025). "We hypothesized that FAP/IL-15 CAR-T cells would specifically recognize and eliminate both FAP-positive tumor cells and CAFs, thereby disrupting stromal components essential for solid tumor progression." (PMID 41455698, 2025). "The second modification was the introduction of a membrane-bound IL-15/IL15R fusion protein (IL-15RF) to enhance in vivo persistence, and the third modification was the addition of an anti-CD19 CAR optimized for NK cells for direct tumor targeting." (PMID 41462483, 2025). "For example, the co-expression of IL-15 and IL-21 enhances survival, proliferation, and functionality, while engineering these cells to express chemokine receptors such as CXCR3 and CCR5 improves their tumour-homing ability." (PMID 40624498, 2025). "IL-15 enhanced the activation of T cells and natural killer cells, while IDO1 inhibitor suppressed Tregs, effectively restoring the IME in LNs and demonstrating potent anti-tumor activity." (PMID 40159756, 2025). "Hence, based on the current findings, we propose a schematic representation to depict the potential mechanisms through which IL-15 and CCL19 augment the functionality of CAR-T cells within the tumor microenvironment." (PMID 40177238, 2025). "IL-13 was induced either upon co-culture with tumor cell lines, or in response to TGF-β and IL-15." (PMID 40114916, 2025). "Nonetheless, final tumor weights between plant-produced Pembrolizumab-IL-15Rα-IL-15 and Keytruda groups were not significantly different (P = 0.31)." (PMID 39808627, 2025). "Localized delivery of eSTING and IL-15/IL-15Rα via ACTM-838 exhibits effective synergistic activity to engage both innate and adaptive immunity in the tumor and generate a durable T-cell mediated systemic anti-tumor immune response." (PMID 41048107, 2025). "In the case of CAR-19 NK-92 cells, armouring with IL-15/IL-15Rα led to enhanced in vitro proliferation (in the absence of IL-2) and in vivo tumour control compared to soluble IL-15." (PMID 41463563, 2025). "The antitumor response of the B16-LX/IL(15 + 7) vaccine was tumor-specific, as it did not inhibit the growth of antigenically distinct EL-4 lymphomas." (PMID 40957993, 2025). "Interestingly, in the NKim subset, expression of IL15 and inhibitory receptor KLRG1 increased significantly with tumor progression; chemokine receptor CXCR3 expression increased with tumor grade in both NKctx and NKim cells." (PMID 40821787, 2025). "To unravel the underlying mechanism, we monitored the proliferation of 4T1 and CTLL‐2 (murine CTL, a pivotal component of adaptive anti‐tumor immunity) in the presence or absence of supplementary IL15c or IL15." (PMID 39625860, 2025). "Tumor-reactive or activated-by-cytokine killers (TRACK) are PD-L1+, highly cytolytic NK cells derived from umbilical cord blood NK cells and engineered to express soluble IL-15 (sIL15), and these cells show promise in preclinical studies against NSCLC." (PMID 39903538, 2025). "This represents a dramatic improvement over conventional IL-15 therapy, which failed to suppress tumor recurrence adequately." (PMID 40791791, 2025). "Deletion of the CIS gene enhances the responsiveness of NK cells to IL-15, thereby promoting their proliferation and survival, increasing IFN-γ secretion, and boosting antitumor cytotoxic activity, ultimately improving the suppression of tumor metastasis." (PMID 40463500, 2025).
tumor (continued). "All CAR constructs used in this study are based on a second-generation CAR designed with 4-1BB as an intracellular costimulatory domain, and all expanded or quiescent CAR T cells were conditioned with human IL-7 and IL-15 post-EP or -LNP and prior to coculture with tumor cells." (PMID 40896578, 2025). "In conclusion, the incorporation of IL-15 and CCL19 into CAR-T cells emerges as a promising strategy to elevate the anti-tumor efficacy of CAR-T cell therapy, positioning 15 × 19 CAR-T cells as a potential breakthrough for enhancing the application of CAR-T therapy in solid tumors." (PMID 40177238, 2025). "Furthermore, the combination of IL-7 and IL-15 plays a crucial role in increasing the number of CD8+CD45RA+CCR7+ within the CAR T cell products, enhancing persistence and anti-tumor activity in preclinical models." (PMID 41346587, 2025). "The single-cell suspensions of the tumor mass or bone marrow were stimulated for 4 h with the NK1.1 antibody or a cytokine cocktail containing IL-12 and IL-15, followed by analysis of NK cell degranulation via CD107a surface expression and NK cell activation by IFNγ staining." (PMID 39885132, 2025). "This design enhances tumor-specific cytotoxicity, optimizes the spatial and temporal co-localization of therapeutic agents, and supports sustained CAR-T cell function through localized IL15 signaling." (PMID 40474210, 2025). "When the ’OR-NOT’ CAR was expressed in NK cells (with IL-15 support), they achieved both a significant reduction in tumour burden and the preservation of healthy cells in vivo." (PMID 41463563, 2025). "For instance, BCMA-CD28-IL15 CAR-NK cells demonstrated more sustained cytotoxic activity and superior control of tumor growth in vivo compared with CAR-NK cells lacking IL-15." (PMID 41303706, 2025). "Tumor-enriched proteases (such as matrix metalloproteinase-2 [MMP2], MMP9, and urokinase plasminogen activator [uPA]3) can cleave the linker and release hemagglutinin (HA)-tagged IL-15 within the TME." (PMID 40532661, 2025). "Interleukin 15 (IL15) is crucial for fostering the survival and proliferation of nature killer (NK) cells and cytotoxic T lymphocytes (CTLs), playing a pivotal role in tumor control." (PMID 39625860, 2025). "Fourth-generation self-inactivating lentiviral vectors were used to deliver a transgenic expression of IFN-α or its co-expression with IL-15 (which induces NK cells expansion, survival, and function), aiming to enhance CAR-GPC3 NK cells’ anti-tumor response against HCC." (PMID 41465318, 2025). "Since NK cell function in the brain is often impaired by hypoxia, adenosine, and inhibitory receptors, combinations such as IL-15 super-agonists, A2A receptor antagonists, and anti-NKG2A antibodies may help restore their anti-tumor activity." (PMID 41219968, 2025). "The combination of IL-15 and CAR T has a superior anti-tumor effect." (PMID 40625735, 2025). "Furthermore, IL-15 is crucial for the sustenance and functionality of memory CD8+ T cells, which are vital for long-term immune surveillance and the prevention of tumor relapse." (PMID 38672104, 2024). "Studies in CISH−/− mice show that NK cells without CISH have better tumor control and IL-15 sensitivity, especially in lung metastasis models." (PMID 39796666, 2024). "The IL-15/IL-15Rα complex secreted from virus-infected tumor cells not only facilitates the recruitment of CAR-NK cells to the tumor site, but also promotes NK cell survival and priming." (PMID 39066359, 2024). "Conversely, the pro-survival cytokine IL15 is essential for maintaining the homeostasis of long-lived CD8+ memory T cells, inhibiting activation-induced cell death, and enhancing in vivo anti-tumor activity." (PMID 39650651, 2024). "Thus, we developed CD33 CAR constructs overexpressing LCK, ZAP70, C-JUN, C-Fos, and IFN-γ, and that overexpressing IL-15, a cytokine known to potentiate CAR T therapeutic activity in various tumor models, as a control." (PMID 39039086, 2024).
tumor (continued). "Our data showed that exogenous IL-15, but not the IL-15-IL-15Rα complex inhibited cell migration, suggesting that the action of exogenous IL-15 requires the presence of tumor cell IL-15Rα and cis-presentation." (PMID 38637902, 2024). "IL-15 administration, like IL-2, has been shown to stimulate NK cell cytotoxicity and promote anti-tumor responses, though with less toxicity and absence of Treg stimulation, which present challenges to IL-2-based therapies." (PMID 38545115, 2024). "However, in contrast to prolonged anti-tumor reactivity by NK:BOB1-TCR/IL-15, we observed in one of the experiments an accumulation of NK:BOB1-TCR/IL-15 cells in several organs of treated mice, leading to unexpected death 30 days post-NK infusion." (PMID 38690288, 2024). "designed GPC3 CAR-T cells co-expressing IL-15 and IL-21 and observed robust expansion and sustained persistence of these T cells in their HCC xenograft models; the resulting tumor control and survival rates were higher than those with CAR-T cells equipped with only one cytokine or the other." (PMID 39430751, 2024). "Its moderate IL-15R affinity and lower potency compared to IL-15 superagonists and even rhIL-15 is considered advantageous, as high affinity IL-15R binding would have negatively interfered with TA-MUC1-mediated tumor accumulation due to fast clearance by a cytokine sink." (PMID 38338686, 2024). "IL-15 plays a vital role in enhancing NK cell- and T-cell-mediated antitumor immune responses; however, the direct effect of IL-15 on tumor cells has not been fully elucidated." (PMID 38637902, 2024). "In addition, previous studies revealed that NK cells are dispensable for IL-12 mRNA-induced anti-tumor immunity in MC38 tumors and that they played a minimal role in eradicating B16F10 tumors during treatment with IL-12/IL15/IFN-α/GM-CSF mRNA cocktail." (PMID 39290693, 2024). "In conclusion, NKG2D CAR-T cells co-expressing IL-15/IL-15Rα promoted the central memory CAR T cell proliferation and improved the homing and persistence of CAR T cells in vivo, resulting in enhanced anti-tumor and anti-viral effects in treating EBV-PTLD." (PMID 39160631, 2024). "The ex vivo stimulation of NK cells with IL-12, IL-15, and IL-18 to generate CIML NK cells has demonstrated superior anti-tumour efficacy in preclinical studies and CIML NK cells are now under assessment in multiple clinical trials for both solid and haematological malignancies." (PMID 38223411, 2024). "The co-expressed IL-15/IL-15Rα complex could prolong the proliferation and survival of NKG2D CAR-T cells, resulting in superior anti-tumor and antiviral effects in EBV-PTLD models." (PMID 39160631, 2024). "Additionally, we show that armoring CD70-CAR NK cells with IL-15 is a prerequisite for effective eradication of low- and high-expressing CD70+ tumor cells and CAFs." (PMID 38331849, 2024). "In our study, the known beneficial effect of IL-15 on NK-mediated cytotoxicity was confirmed by slightly improved effector functions of control NK:CMV-TCR/IL-15 cells, that exhibited an increased anti-tumor reactivity in vitro compared to NK:CMV-TCR cells." (PMID 38690288, 2024). "FCRL5/IL-15 CAR-T cells promoted a shift towards the TCM phenotype while reducing PD-1 exhaustion, which may facilitate more durable and potent anti-tumor responses, thus potentially overcoming the limitations of BCMA-targeted therapy." (PMID 38212320, 2024). "The interleukin-15 superagonist N-803 demonstrated to be active in activating NK cells for SCLC cell lysis independently on MHC-I expression and thus activating a response even in immunologically cold tumours." (PMID 39215193, 2024). "Further investigation into the regulatory process of LAMP3+ DCs in tumors revealed that tumor-infiltrating LAMP3+ DCs have lower expression of IL15 compared to those in adjacent non-tumor tissue." (PMID 38552055, 2024).
tumor (continued). "Among the actions generated putatively through MDA5 are a further increase in Type 1 IFN, depression of MDSC, expansion of CD8 T cell populations through IL-15, CD8 targeting and infiltration of tumor through CXCL10, and a direct Type 1 IFN-dependent effect on tumor endothelium through VCAM-139." (PMID 38719809, 2024). "In this study, we demonstrated that the infection of B16F10 tumor cells with the rLaSota-BC-RFP virus increased the infiltration of CD8+ and CD4+ T cells in the tumor tissues, accompanied by elevated levels of IL-12, IFN-γ, IL-15, TNF-α, and IL-18." (PMID 39458338, 2024). "According to the author, anti-PD-1 antibodies reacted and activated only tumor antigen–specific cells, whereas IL-15 was activated regardless of antigen specificity." (PMID 39507777, 2024). "This suggested that the benefit to the NK cells was provided by enhanced IL-15 signaling during hypoxia, not just because of the enhanced tumor targeting through CD16 that a TriKE provides." (PMID 39475618, 2024). "Unlike IL-15 overexpression within tumor cells, exogenous IL-15 did not affect the formation of pseudopodia in A549 cells or PC9 cells; however, compared with that in untreated cells, the number of stress fibers in tumor cells was significantly lower." (PMID 38637902, 2024). "The failure of the IL-15/IL-15Rα complex in the treatment of cancer has not been considered to date in light of its actions on tumor cells." (PMID 38637902, 2024). "In the NCI-H929-luc subcutaneous model, both FCRL5-targeted CAR-T cell treatments initially attenuated tumor progression; however, FCRL5 CAR-T/IL-15 demonstrated enhanced therapeutic sustainability, with mice experiencing prolonged survival until the conclusion of the study." (PMID 38212320, 2024). "The construct demonstrated strong tumor growth inhibitory effect in the B16 metastasis model compared to untargeted IL-15 or compared to the construct without the sushi domain." (PMID 39204319, 2024). "Furthermore, in animals bearing peritoneal MC38 CRC, a novel oncolytic vv expressing the superagonist IL-15, a fusion protein of IL-15 and IL-15R-α(vvDD-IL15-Ra, IV administration) significantly reduced tumor growth and extended survival." (PMID 38596287, 2024). "Based on the effects of NKG2D CAR and IL-15/IL-15Rα on virus-infected cells and tumor cells, as well as the NKG2DL expressions on B-LCL cells of EBV-PTLD mouse models, we propose IL-15/IL-15Rα co-expressing NKG2D CAR-T for the treatment of EBV PTLD - an approach that has not been reported thus far." (PMID 39160631, 2024). "Preclinical studies performed in vitro and in mouse models with orthotopic NB have demonstrated that integration of IL-15 and IL-21 in a NB immunotherapy regimen (with anti-GD2 and GM-CSF) exhibits anti-tumor activity and outperforms the anti-GD2-IL-2 combination." (PMID 39294470, 2024). "Also, the Pavlakis group showed that multiple peri-tumoral injections of hetIL-15, the heterodimeric IL-15/IL-15Rα in EO771 TNBC tumors resulted in significant tumor regression, increased host survival and prevention or elimination of metastasis." (PMID 39559362, 2024). "Finally, since enhanced IL-15 signaling impacts both CD8 T cells and NK cells, we sought to determine the NK cell contribution to the enhanced control of tumor growth after treatment." (PMID 38267402, 2024). "IL-15-activated NK cells, employing antibodies to promote antibody-dependent cellular cytotoxicity (ADCC), are a novel method of killing tumor cells circumventing tumor immune escape." (PMID 38604154, 2024). "CAR T cells overexpressing IL-15 showed enhanced expansion in mice but unfortunately did not control tumor progression as effectively as other molecules." (PMID 39039086, 2024). "The expression of IL-15, for instance, improved the persistence and proliferative capacity of IL-13Rα2-CAR-T cells in a preclinical glioma model and, thus, led to a stronger anti-tumor activity." (PMID 37443804, 2023).
tumor (continued). "However, it is important to note that the expression of IL15, a crucial factor in activating NK cells and enhancing the anti-tumor activity of CD8+ T cells, is significantly higher in tumor cells compared to Netrin G1." (PMID 38099290, 2023). "However, only the combination treatment (cyto-IL-15 and ADU) led to complete tumor regression (98% volume reduction), had the greatest impact on survival (undefined, p < 0.001) and complete cured 4 out of 6 mice (67%)." (PMID 37465665, 2023). "In summary, the spatiotemporally synchronous presentation of IL-15 and tumor antigen prevented non-specific systemic immune stimulation, thus avoiding systemic side effects." (PMID 37875481, 2023). "They added IL15 to the BiKE and called it 161533, wherein the TriKE facilitates the formation of a synapse between the NK cell (CD16) and the tumor cell (CD33), binding to the CD16 on the NK cells to trigger ADCC and the IL15 will promote NK cell activation and expansion." (PMID 37228595, 2023). "This was corroborated by a study that utilized aerobic training, which not only attenuated muscle wasting but also decreased tumor volume, mitigating levels of inflammatory markers such as the IL-10 and TNF-α ratio, along with IL-15 expression in skeletal muscle, in 4T1 cachectic breast cancer mice." (PMID 37755304, 2023). "IL-15 was shown to determine both the number and the activity of tumor-infiltrating NK cells and CD8+ T cells, and multiple clinical studies are currently studying the use of IL-15 as an anti-tumor therapy." (PMID 37348499, 2023). "The researchers linked IL‐15 and IL‐21 to the anti‐GD2 antibody hu14.18 and found that the two‐novel antibody–cytokine conjugates, hu14.18‐IL15 and ‐IL21, were able to induce complete regression and prolong survival in NB tumor models, which had a stronger ADCC effect than hu14.18‐IL2." (PMID 38090056, 2023). "Treatment with IL-15 as monotherapy has been shown ineffective due to immune checkpoints and due to the lack of tumor-specific targeting of NK cells." (PMID 37923822, 2023). "Our findings also highlight the importance of IL15 use for CD226 expression and T cell functionality restoration and that this cytokine may be included in immunotherapeutic strategies to increase tumor control." (PMID 36717657, 2023). "Similar to IL-15, injection of long-acting IL-7 together with CAR-T cells could extend the survival of tumor-bearing animals in both xenograft and immunocompetent mouse models." (PMID 36768665, 2023). "MCAR15-Vδ2T cells resulted in complete remissions in all 5/5 mice through day 180 without any signs of GvHD, highlighting the benefit of IL-15 engineering in long-term intraperitoneal tumor growth inhibition." (PMID 37938576, 2023). "The weak interaction with tumor-specific T cells of IL-15 raises the risks of nontumor-specific immune activation, leading to systemic side effects and a deficiency of tumor suppression." (PMID 37875481, 2023). "In addition to the PD-1 molecule, cytokine-inducible Src homology 2–containing (CIS) protein, a key inhibitor of IL-15 signaling, has been knocked out by the CRISPR/Cas9 system in CAR-NK cells to improve anti-tumor ability." (PMID 37144558, 2023). "BiKEs target a tumor antigen and another functional element on the NK cell membrane, e.g., CD16, NKG2D, and NKp46, while TriKEs target one more element (commonly a tumor antigen or IL-15)." (PMID 36761751, 2023). "Thus, we propose that the presence of mbIL-15 and secreted IL-15/IL-15Rα complexes could in early tumor stages promote the production of cytotoxic lymphocytes cells (T and NK cells), but promote the accumulation of dysfunctional tumor infiltrated lymphocytes in stage IV." (PMID 37334356, 2023). "These anti-CD19 CAR-NK cells were capable of expressing IL-15 ectopically and showed enriched proliferation, persistence, homing, and cytotoxicity against tumour targets in vivo compared to those without IL-15 expression." (PMID 36765526, 2023).